ATP6AP1 (ATPase H+ transporting accessory protein 1)
Description:
Accessory subunit of the V0 complex of vacuolar(H+)-ATPase (V-ATPase), a multisubunit enzyme composed of a peripheral complex (V1) that hydrolyzes ATP and a membrane integral complex (V0) that translocates protons. V-ATPase is responsible for acidifying and maintaining the pH of intracellular compartments and in some cell types, is targeted to the plasma membrane, where it promotes acidification of the extracellular environment. The V-ATPase complex also acts as an activator for mTORC1 on lysosomal membrane by promoting the guanine nucleotide exchange factor (GEF) of the Ragulator complex, thereby enabling mTORC1 recruitment. Guides the V-type ATPase into specialized subcellular compartments, such as neuroendocrine regulated secretory vesicles or the ruffled border of the osteoclast, thereby regulating its activity. Involved in membrane trafficking and Ca(2+)-dependent membrane fusion. May play a role in the assembly of the V-type ATPase complex (Probable). In aerobic conditions, involved in intracellular iron homeostasis, thus triggering the activity of Fe(2+) prolyl hydroxylase (PHD) enzymes, and leading to HIF1A hydroxylation and subsequent proteasomal degradation. In islets of Langerhans cells, may regulate the acidification of dense-core secretory granules (By similarity).
Synonyms: ATP6IP1; ATP6S1; VATPS1; XAP3; ORF; XAP-3; 16A; Ac45; CF2
Tractability: Small molecule: a structure with a bound ligand is known. Antibody: UniProt predicts a signal peptide or a membrane-spanning region. PROTAC: ubiquitination databases record sites on it; its protein half-life has been measured; a small molecule that binds it is known.
Target class: Enzyme; Hydrolase
Gene: Protein-coding gene on chromosome X (154,428,618 to 154,436,517, forward strand). Ensembl gene ENSG00000071553.
Subcellular location: Endoplasmic reticulum membrane; Endoplasmic reticulum-Golgi intermediate compartment membrane; Cytoplasmic vesicle, secretory vesicle, synaptic vesicle membrane; Cytoplasmic vesicle, clathrin-coated vesicle membrane
Pathways (Reactome):
Signal Transduction: Insulin receptor recycling; RHOA GTPase cycle
Transport of small molecules: Ion channel transport; Transferrin endocytosis and recycling
Gene Ontology:
Molecular function: guanyl nucleotide exchange factor activator activity; protein binding; small GTPase binding; molecular function activator activity
Biological process: cellular response to amino acid stimulus; cellular response to increased oxygen levels; intracellular iron ion homeostasis; positive regulation of TORC1 signaling; endosomal lumen acidification; endosome to plasma membrane protein transport; Golgi lumen acidification; intracellular pH reduction; lysosomal lumen acidification; osteoclast development; proton transmembrane transport; vacuolar acidification; synaptic vesicle lumen acidification
Cellular component: endoplasmic reticulum membrane; endoplasmic reticulum-Golgi intermediate compartment membrane; extracellular exosome; lysosomal membrane; lysosomal proton-transporting V-type ATPase complex; membrane; endosome membrane; Golgi membrane; plasma membrane; proton-transporting two-sector ATPase complex; proton-transporting V-type ATPase complex; bounding membrane of organelle; clathrin-coated vesicle membrane; cytoplasmic vesicle membrane; endomembrane system; synaptic vesicle membrane
Gene-disease validity (ClinGen):
ClinGen rates the evidence that ATP6AP1 causes each of these diseases.
congenital disorder of glycosylation type II (X-linked): Definitive. A congenital disorder of glycosylation that involves malfunctioning trimming/processing of the protein-bound oligosaccharide chain.
Homologues: Orthologues: chimpanzee ATP6AP1 (99% identical), macaque ATP6AP1 (99% identical), dog ATP6AP1 (89% identical), rabbit ATP6AP1 (89% identical), pig ATP6AP1 (86% identical), mouse Atp6ap1 (86% identical), guinea pig ATP6AP1 (85% identical), rat Atp6ap1 (82% identical), tropical clawed frog atp6ap1.2 (54% identical), zebrafish atp6ap1a (46% identical), zebrafish atp6ap1b (44% identical), Drosophila melanogaster VhaAC45 (19% identical), and 1 more.
Diseases named in the same sentence as ATP6AP1 in open-access papers:
ATP6AP1 is named in the same sentence as 64 diseases in open-access papers, as found by Europe PMC text mining. Sharing a sentence is not in itself a finding about the gene and the disease. The quoted sentences say what the papers report.
breast carcinoma (13 papers, 2016 to 2025). "Consistent with this, we found that ATP6AP1 overexpression in luminal breast cancer was associated with poor patient outcomes." (PMID 40133274, 2025). "Here, we found that ATP6AP1 overexpression in luminal breast cancer is associated with poor patient outcomes." (PMID 40133274, 2025). "Given autophagy flux especially the autophagosome-lysosome fusion process association with DOX resistance and higher expression of lysosome related gene ATP6AP1 in breast cancer tissues, we investigated association of ATP6AP1 with DOX resistance." (PMID 39627767, 2024). "Elevated ATP6AP1 expression was consistently observed in breast cancer subtypes associated with poorer clinical outcomes, particularly in patients showing reduced responsiveness to neoadjuvant chemotherapy." (PMID 39627767, 2024). "ATP6AP1 was upregulated in breast cancer tissues, and higher ATP6AP1 expression was associated with poorer outcomes." (PMID 38369634, 2024). "Through comprehensive analysis of autophagy-lysosomal gene expression, we identified that the lysosome-associated gene ATP6AP1 is consistently upregulated in breast cancer tissues and associated with worse clinical outcomes." (PMID 39627767, 2024). "Although V-ATPases have been proven to be carcinogenic in certain neoplasms, the prognostic value and underlying mechanism of ATP6AP1 in breast cancer need to be fully characterized." (PMID 36147483, 2022). "Univariate Cox regression analysis revealed an association between ATP6AP1 and breast cancer prognosis." (PMID 36147483, 2022). "In conclusion, there was a significant increase in ATP6AP1 expression in breast cancer tissues, and greater ATP6AP1 expression was associated with poor prognosis." (PMID 36147483, 2022). "Moreover, ATG5 knockdown effectively prevented the increase in luminal breast cancer cell proliferation caused by ATP6AP1 overexpression." (PMID 40133274, 2025). "Furthermore, we examined the association between tumor immune infiltration and ATP6AP1 expression in breast cancer." (PMID 36147483, 2022). "In this study, we investigated the association between ATP6AP1 and breast cancer." (PMID 36147483, 2022). "High expression of ATP6AP1 in breast cancer is associated with poor prognosis." (PMID 36077333, 2022). "Based on the ROC analysis, the AUC was 0.939, suggesting that ATP6AP1 expression could have potential diagnostic value in distinguishing breast cancer from normal tissues." (PMID 36147483, 2022). "We investigated the association of ATP6AP1 with breast cancer (BC) and COVID-19." (PMID 34228637, 2021). "Moreover, survival analysis subtypes from the Kaplan‒Meier Plotter database showed that high ATP6AP1 expression was associated with poor patient outcomes in luminal breast cancer, while it was insignificant in HER2+ or basal, consistent with findings from the bc-GenExMiner tool." (PMID 40133274, 2025). "The area under the curve (AUC) of ATP6AP1 expression for distinguishing tumors from normal tissues was 0.939 on the ROC curve, indicating that ATP6AP1 might be a potential diagnostic marker for breast cancer." (PMID 36147483, 2022). "ATP6AP1 may be a new diagnostic, therapeutic, and prognostic target for breast cancer treatment." (PMID 36147483, 2022). "Combined, these data indicate that ATP6AP1 overexpression promotes luminal breast cancer cell proliferation and TAM resistance through autophagy activation." (PMID 40133274, 2025). "ATP6AP1 overexpression enhanced cell proliferation, whereas ATP6AP1 depletion reduced cell proliferation, indicating that ATP6AP1 promotes luminal breast cancer cell proliferation in vitro." (PMID 40133274, 2025). "While ATP6AP1 has been identified as a biomarker in breast cancer, its function in breast cancer is still not well understood." (PMID 40133274, 2025). "Together, our studies identify ATP6AP1 as a crucial regulator of autophagy, potentially serving as a valuable prognostic marker or therapeutic target in human luminal breast cancer." (PMID 40133274, 2025).
breast carcinoma (continued). "Previous research identified ATP6AP1 as a breast cancer-specific biomarker for early detection and was recently found to be a potential prognostic biomarker." (PMID 40133274, 2025). "We discovered that ATP6AP1 enhances the TAM resistance of luminal breast cancer cells by activating autophagy." (PMID 40133274, 2025). "We further demonstrated that ATP6AP1 promotes the proliferation of human luminal breast cancer cells and enhances tamoxifen (TAM) resistance by activating autophagy." (PMID 40133274, 2025). "To further validate the role of ATP6AP1 in cell proliferation and TAM sensitivity, we established breast cancer xenograft mouse models using ZR-75-1 cells stably overexpressing ATP6AP1 or a control vector." (PMID 40133274, 2025). "To investigate the role of ATP6AP1 in luminal breast cancer cell proliferation, we generated cell lines with ATP6AP1 overexpression (ZR-75-1 and T47D cells) or knocking down (MCF-7 and BT-474 cells) using lentivirus." (PMID 40133274, 2025). "The expression of ATP6AP1 in breast cancer subtypes obtained from scRNA-seq showed that the luminal subtype of breast cancer had the highest ATP6AP1 transcript levels among all subtypes." (PMID 40133274, 2025). "In this study, we found that ATP6AP1 is overexpressed in luminal breast cancer tissues and promotes the proliferation and tamoxifen resistance of luminal breast cancer cells both in vitro and in vivo." (PMID 40133274, 2025). "The results demonstrated significantly higher ATP6AP1 protein expression in luminal breast cancer tissues compared to adjacent breast tissues." (PMID 40133274, 2025). "In our study, we revealed that ATP6AP1 overexpression promotes luminal breast cancer cell proliferation and TAM resistance by activating autophagy." (PMID 40133274, 2025). "Although we have preliminarily clarified the role of ATP6AP1-mediated autophagy in breast cancer drug resistance through cell experiments and similar methods, we have not conducted a thorough and comprehensive analysis of its underlying mechanisms." (PMID 39627767, 2024). "Knocking down ATP6AP1 reduces autophagy-mediated doxorubicin resistance by inhibiting autophagic flux and lysosomal acidification in breast cancer cells." (PMID 39627767, 2024). "Higher ATP6AP1 expression is also correlated with more advanced cancer stage and poorer prognosis in breast cancer patients." (PMID 38448650, 2024). "In this study, we demonstrated that ATP6AP1-mediated autophagy played a critical role in breast cancer chemoresistance." (PMID 39627767, 2024). "The lysosomal gene ATP6AP1 facilitates autolysosome acidification and contributes to doxorubicin resistance in breast cancer." (PMID 39627767, 2024). "ATP6AP1 was primarily found at high levels of expression in breast cancer cell lines (MCF-7, T-47D, ZR-75-1 and MDA-MB-453)." (PMID 39627767, 2024). "The lysosomal gene ATP6AP1, which plays a role in autophagic processes, is upregulated in breast cancer tissues." (PMID 39627767, 2024). "Through a comprehensive analysis of autophagy-lysosomal gene expression profiles, we identified ATP6AP1 as a key regulator of autophagy in breast cancer cells, contributing significantly to resistance against DOX." (PMID 39627767, 2024). "Our data further revealed that knocking down ATP6AP1 in breast cancer cells significantly increased sensitivity to DOX by inhibiting autophagy." (PMID 39627767, 2024). "We found that protein levels of ATP6AP1 were elevated in multiple breast cancer cell lines, such as MDA-MB-231, MDA-MB-436, and MCF7, compared with the non-tumorigenic MCF10A cell line." (PMID 38448650, 2024). "This study aims to elucidate the role of the lysosomal gene ATP6AP1 in promoting chemoresistance in breast cancer by upregulating autophagic flux." (PMID 39627767, 2024). "To investigate the potential role of ATP6AP1 in the chemosensitivity of breast cancer cells, we stably knocked down ATP6AP1 in T-47D and MDA-MB-453 cells." (PMID 39627767, 2024).
breast carcinoma (continued). "Inhibiting ATP6AP1 by blocking autophagy can increase drug sensitivity in breast cancer cells, thereby improving the therapeutic outcomes and overall survival of breast cancer patients." (PMID 39627767, 2024). "Breast cancer cells were infected with shRNA lentivirus targeting ATP6AP1, allowing investigation its tole in doxorubicin-induced cell death." (PMID 39627767, 2024). "The functional modules of LinkedOmics were used to detect genes that were co-expressed with ATP6AP1 in breast cancer to further understand ATP6AP1’s biological functions in the disease." (PMID 36147483, 2022). "To further understand the impact of ATP6AP1 in breast cancer, we used GO and KEGG functional enrichment analyses to evaluate co-expressed genes." (PMID 36147483, 2022). "We developed a novel GRG signature of six GRGs, including CACNA1H, CHPF, IRS2, NT5E, SDC1 and ATP6AP1, to predict survival and guide individual therapy in breast cancer." (PMID 36277284, 2022). "StromalScore, ImmuneScore, and ESTIMATEScore were significantly lower in “high ATP6AP1 expression” breast cancer patients relative to “low ATP6AP1 expression” breast cancer patients (p < 0.001)." (PMID 36147483, 2022). "Our results suggest that the ATP6AP1 levels in breast cancer tissues were substantially higher than those in normal breast tissues." (PMID 36147483, 2022). "We developed a nomogram to aid in the prediction of breast cancer patient prognosis, which included ATP6AP1 expression levels and clinicopathological parameters that were significant in Cox regression analyses." (PMID 36147483, 2022). "Detecting the genes co-expressed with ATP6AP1 helped us gain a better understanding of ATP6AP1’s biological activities in breast cancer." (PMID 36147483, 2022). "In the TCGA-BRCA, GSE45827, and GSE42568 datasets, ATP6AP1 expression was substantially lower in normal tissues than in breast cancer tissues (p < 0.001)." (PMID 36147483, 2022). "ATPase H+ Transporting Accessory Protein 1 (ATP6AP1), which is a component of a multi-subunit enzyme in Vacuole ATPase (V-ATPase), is highly expressed in breast cancer tissues." (PMID 36364157, 2022). "A nomogram based on ATP6AP1 and other clinicopathological parameters was constructed to help clinicians predict the prognosis of patients with breast cancer." (PMID 36147483, 2022). "We further analyzed the effect of ATP6AP1 expression on the immunological characteristics of breast cancer patients in TCGA-BRCA." (PMID 36147483, 2022). "Based on data from the Human Protein Atlas (HPA) database, the level of ATP6AP1 protein expression in breast cancer tissues was significantly higher than in normal breast tissues." (PMID 36147483, 2022). "A PPI network, including ATP6AP1 and its co-expression genes, was constructed, and the TFs and miRNAs related to ATP6AP1 in breast cancer were identified." (PMID 36147483, 2022). "Endocrine therapies such as tamoxifen are classical treatments for ERα-positive breast cancer, especially for Luminal A subtype, therefore, we verified whether ATP6AP1 would have an effect on the drug sensitivity of TAM-treated luminal breast cancer cells." (PMID 40133274, 2025). "Furthermore, we used CQ to inhibit autophagy in ATP6AP1-overexpressing breast cancer cells and analyzed the impact on TAM-induced apoptosis." (PMID 40133274, 2025). "Furthermore, we assessed ATP6AP1 protein levels in primary human luminal breast cancer samples and matched adjacent breast tissue samples using immunohistochemistry (IHC)." (PMID 40133274, 2025). "Furthermore, the lysosomal gene ATP6AP1 has been demonstrated to confer doxorubicin resistance in breast cancer through the upregulation of autophagic flux." (PMID 41450825, 2025). "In order to elucidate the role of ATP6AP1 in luminal breast cancer, we selected luminal breast cancer cell lines for subsequent studies, including ER-positive, PR-positive luminal A cells MCF-7, T47D, ZR-75-1, and ER-positive, HER2-positive luminal B cells BT-474." (PMID 40133274, 2025).